TLR4 (toll like receptor 4)
Diseases named in the same sentence as TLR4 in open-access papers (continued):
Sharing a sentence is not in itself a finding about the gene and the disease.
cancer (continued). "SBsib-711 from a blackfly is a TLR4/MD2 ligand used as a cancer vaccine immunoadjuvant." (PMID 38399416, 2024). "Having confirmed that heparanase is essential for mast cell capability to promote cancer cell stem-like features, we hence hypothesized that heparan sulfate could be responsible for the observed effect by TLR4 activation." (PMID 39349458, 2024). "Indeed, increased expression of TLR4 has been shown to induce cell proliferation, migration, invasion, and survival, protecting cancer cells against apoptosis and immune surveillance." (PMID 39451550, 2024). "However, oxaliplatin seems to induce immunogenic signals on the surface of cancer cells before apoptosis, triggering interferon-gamma production and interaction with toll-like receptor 4 on dendritic cells, resulting in the immunogenic death of cancer cells." (PMID 38177168, 2024). "According to our speculation, TLR4 activation with another agonist would have been sufficient to promote the stem-like features of cancer cells also in the presence of inactive mast cell heparanase activity." (PMID 39349458, 2024). "TLR4 signaling promotes the activation of hepatic stellate cells, leading to increased extracellular matrix production and fibrosis, which creates a tumorigenic environment, promoting the transition from liver damage to cancer." (PMID 39335657, 2024). "As hypothesized, heparanase and TLR4 inhibition resulted in reduced capacity of cancer cells to form spheroids, although heparan sulfate itself and TLR4 agonist increased this effect." (PMID 39349458, 2024). "A pan-cancer analysis identified TLR4 and TLR5 as prognostic genes in ACC." (PMID 36899891, 2023). "To date, S100A8 expression or overexpression of TLR4 has been observed in various cancers." (PMID 36932197, 2023). "MIF is a pro-inflammatory cytokine found in macrophages, vascular endothelial cells, tissue epithelial cells, and cancer cells and influences innate immunity via TLR4 by recruiting immune cells to inflammatory locations, activating inflammatory pathways, and inducing immune cell differentiation." (PMID 37675176, 2023). "The cancer cells in TLR2−/− mice were remained epithelioid phenotype while in TLR4−/− mice, PepO could effectively inhibit the EMT." (PMID 37925462, 2023). "There existed an assumption that TLR4 may play two entirely antithetical roles when solely expressed on cancer cells or immune cells." (PMID 37553698, 2023). "Activation of TLR4-NF-B under inflammatory conditions induces cancer cell motility and invasion." (PMID 36936437, 2023). "In conclusion, inducing TLR-4 dimerization is an emerging cancer immunotherapy approach." (PMID 37103820, 2023). "TLR4 functions as a link between bacterial infection, colonic inflammation, and cancer progression." (PMID 37509740, 2023). "Aberrant expression of TLR4 has been observed in many types of cancer." (PMID 36840233, 2023). "Current study supports the notion that the discovery of JAK3 and TLR4 antagonists could be an ideal strategy for cancer treatment." (PMID 38149248, 2023). "As we know TLR4/MyD88 signaling plays vigorous roles in several cancers." (PMID 37822929, 2023). "By blocking or reducing TLR4 activation, developing new treatments that target cancer cells and reverse resistance may be possible." (PMID 37701157, 2023). "Finally, a pan-cancer analysis demonstrated TLR4 had differential expression in various malignancies in comparison with normal tissue samples." (PMID 37576399, 2023). "TLR4 is also reported to be intimately involved in cancer progression, and recent work shows that it may play an important role in MM pathogenesis." (PMID 36625202, 2023). "Conversely, SOCE activation enhanced the TLR4 induction of these cancer processes." (PMID 37371732, 2023). "Inhibition of TLR4 by siRNA and NF-B inhibitors can reduce cancer cell invasiveness." (PMID 36936437, 2023).
cancer (continued). "In addition, the expression levels of IL-6, IL-17, TNF-α,IL-12β, TLR-2, and TLR-4 as well as miR-21 and miR-31 showed a significant increase in the cancer group." (PMID 38075864, 2023). "It was demonstrated that the functional suppression of ER-ɑ using an antagonist Tx could enhance the expression of TLR4 in cancer cells." (PMID 36902278, 2023). "Although TLR sensing of MuPyV has not been extensively studied, one study demonstrated a direct interaction between MuPyV VP1 and murine TLR4 in primary and untransformed mouse embryonic fibroblasts and showed that TLR4-mediated recognition of the virus led to cancer-like phenotypes." (PMID 37896889, 2023). "It has been detected that TLR-3 and TLR-4 are highly expressed in cancer cells." (PMID 38090147, 2023). "Even though therapeutic options based on TLRs other than TLR4 have reached the stage of clinical trials for OC, there are still not enough to draw firm conclusions, since the expression of TLRs on immune cells and cancer cells seem to exert opposite effects." (PMID 36983067, 2023). "The pathological mechanisms of various diseases such as chronic gastrointestinal diseases and malignant tumors are related to abnormal activation of Toll-like receptor 4, and all suggest that the transduction mode of the Toll-like receptor 4 signaling pathway is complex and fine." (PMID 37207228, 2023). "HMGB1, as a DAMP released by cancer cells, can efficiently activate TLR4." (PMID 36911674, 2023). "By contrast, a large proportion of cancer cells in HCC tissues showed increased TLR4 expression." (PMID 37896221, 2023). "In fact, TLR4 signaling is also involved in drug resistance and cancer cell proliferation." (PMID 37701157, 2023). "Moreover, F. nucleatum in CRC activated TLR4 to enhance autophagy in cancer cells and thus conferring chemoresistance." (PMID 37771912, 2023). "Messaritacis et al28 hypothesized that the presence of TLR2, TLR4, and TLR9 variants affected gut homeostasis resulting in impairment of TLRs activation, thus leading to inflammation and cancer development and progression." (PMID 37404119, 2023). "In TLR4-transfected cancer coli-2 (Caco-2) cells, the TLR4 signaling pathway upregulates PPARγ expression as well as the expression of a PPARγ-dependent reporter in an inhibitor of nuclear factor kappa-light-chain-enhancer of activated B cells (Iκβ)-dependent manner." (PMID 35222098, 2022). "Not only can the function of TLR4 be explained as a pivotal regulator in innate and acquired immunity but can also be regarded as linking to the occurrence and development of multifarious cancers." (PMID 36008864, 2022). "Studies have shown that 20% of cancer-related deaths were directly due to TLR-induced cancer cachexia, in which cancer cells released heat shock proteins that acted as TLR-4 agonists in macrophages, skeletal muscle, and fat cells, causing downstream signal transduction." (PMID 36545470, 2022). "Next, a flow cytometry-based PBMC cytotoxicity assay was utilized to delineate whether either stimulation of NOD1 alone or a combined stimulation of NOD1 and TLR4 can strengthen the cytolytic activity of PBMCs and NK cells against K562 cancer cells." (PMID 35935855, 2022). "In addition, the upregulation of TLR4 and TLR2 was found to be positively associated with increases in PD-L1 or PD-L2 in infection and cancer." (PMID 36131933, 2022). "To determine if MyD88 transduces LPS/TLR4 signaling to induce cancer apoptosis in the presence of an IAP antagonist, we investigated the effect of a small molecular compound, called 4210, which blocks MyD88 dimerization, on the apoptosis of MDA-MB-231 cells induced by LPS+SM-164." (PMID 36119107, 2022). "In several cancers, TLR4 has been indicated to play a significant role." (PMID 36030212, 2022). "As already mentioned, the activation of TLR-4 may act as a double-edged sword in cancers; that is, TLR-4 activation has been involved in both cancer suppression and cancer growth." (PMID 36142391, 2022).
cancer (continued). "MSNs combined with anti-PD-1 for cancer therapy, promote cytotoxic T lymphocyte infiltration through TLR4-NFκB axis and lead to in vitro and in vivo Ccl5/Cxcl9/Cxcl10 production to overcome anti-PD-1 resistance, to establish a T-cell inflammatory microenvironment." (PMID 36365103, 2022). "Several studies have suggested an association between TLR4 and cancers, but some studies have not suggested the same results." (PMID 36281200, 2022). "Clinical application of BCG and monophospho lipid A (MPLA) as TLR4 agonists for cancer therapy." (PMID 36365103, 2022). "Here, we clearly identified TLR4, which is expressed on cancer cells, as a receptor for PAUF." (PMID 36232715, 2022). "To date, S100A8 expression, or overexpression of TLR4, was observed in various cancers." (PMID 35780158, 2022). "Furthermore, augmented expression of TLR4 in several immunogenic cancer types predicts positive survival prognosis." (PMID 36678520, 2022). "Outcomes of data analysis on the relationship between TLR4 and cancers." (PMID 36281200, 2022). "Moreover, MPLA is the only TLR4 agonist that has been clinically tested as an adjuvant for cancer vaccines." (PMID 35464417, 2022). "In addition, B7-H3 stimulates VEGF and IL-8 secretion via the TLR4/NF-B pathway, supporting the view that B7-H3 promotes cancer invasion and metastasis." (PMID 36605103, 2022). "To confirm whether PAUF can bind directly to TLR4 on the surface of cancer cells, we performed proximity ligation assay (PLA)." (PMID 36232715, 2022). "Notably, TLR4 agonists have aroused widespread concern as a brilliant immunotherapeutic for the treatment of cancer." (PMID 35911966, 2022). "Toll-like receptor 4 (TLR4) is commonly overexpressed in barrier epithelial cells and cancer." (PMID 36092893, 2022). "TLR4 has been shown to exert immunosuppressive properties in different types of cancer." (PMID 35327577, 2022). "TLR7 expression is moderate in pan-cancer, lower than that of TLR4." (PMID 35801728, 2022). "Herein, we postulate that stimulation of NOD1 alone or a combined stimulation of NOD1 and TLR4 could also strengthen PBMC-mediated cytotoxicity against cancer cells." (PMID 35935855, 2022). "Therefore, the development of molecularly defined, homogeneous TLR4 agonists which are safe and well tolerated in humans as potential stand-alone therapeutics for cancer or as supplements in checkpoint inhibitor treatment is highly required." (PMID 36678520, 2022). "Importantly, LPS sensitizes the therapeutic response of both TNBC and ER+ BC to IAP antagonist therapy by inducing the cancer cell apoptosis through toll-like receptor 4 (TLR4) and MyD88 stimulated TNFα production." (PMID 36119107, 2022). "Although a role of MiR-205 in human cancer is controversial, overexpression of MiR-205 in human corneal epithelial cells has been shown to protect against UV-induced corneal damage by targeting Toll-like receptor 4 (TLR4)." (PMID 36567017, 2022). "Studies have shown that TLR4 is also highly expressed in various cancer cells, including PC cells, and may promote the proliferation and invasion of PC through the up-regulation of HIF-1α and is closely related to prognosis." (PMID 35309293, 2022). "TLR4 has been identified as a potential drug target for the immuno-therapeutics in various cancers." (PMID 33585082, 2021). "The activation of TLR4/NFκB signaling pathway upon palmitic acid challenge may be due to the elevated expressions of the TLR4 in the cancer cells." (PMID 34385421, 2021). "Compared with the existing TLR4 gene-related experiments, our work comprehensively and systematically studied the expression of the TLR4 gene in pan-cancer and screened out cancer types with a poor prognosis, which will provide reference data for follow-up studies." (PMID 34631699, 2021). "AS15 is a TLR4 agonist and is employed as a cancer vaccine adjuvant." (PMID 34671606, 2021).
cancer (continued). "Collectively, TLR4 recognition of MPyV induces a cytokine environment that promotes the cancer-associated fibroblast (CAF)-like phenotype in noninfected fibroblasts and increases cell invasiveness." (PMID 33923020, 2021). "TLR4 is increasingly recognized as playing important roles in cancer." (PMID 34771442, 2021). "In cancer cachexia, the activation of TLRs by DAMPs, released in the bloodstream, stimulates muscle proteolysis both directly, by acting on muscle cells, and indirectly, by activating TLR4 in immune cells to increase systemic inflammation." (PMID 33419963, 2021). "Furthermore, data in the literature reported also that NF-κB, a key positive regulator of PD-L1 expression in cancer, is activated by TLR4." (PMID 34829995, 2021). "Furthermore, TLR4 activation is involved in the promotion of several cancers, such as cervical, colorectal, and prostate cancer." (PMID 34884547, 2021). "It is worth noting that the membrane receptor Toll-like receptor 4 (TLR4) has been reported to mediate cancer-induced muscle atrophy by activating the protein degradation pathway in the muscle of Lewis lung cancer (LLC) mice and stimulating the innate immune response." (PMID 34552592, 2021). "Dysregulation of TLR4 signalling has been shown to play a role in the initiation and/or progression of various diseases, such as ischaemia-reperfusion injury, atherosclerosis, hypertension, cancer, and neuropsychiatric and neurodegenerative disorders." (PMID 33505220, 2021). "Our study suggests that TLR4 reprograms CRC metabolism that may affect the cancer growth, this notion agrees with our findings that HFD fails to increase the growth of the TLR4-knockout CRC." (PMID 34385421, 2021). "Furthermore, the interaction between PRDX1 and TLR4 in human cancer cells was shown to upregulate HIF-1α, a master regulator of adaptive responses to hypoxia that is highly expressed in NES tissues (Allen and Vázquez-Medina, 2019)." (PMID 34744798, 2021). "Aberrant expression of TLR4 was also observed in many types of cancer." (PMID 34444754, 2021). "This study suggests that oxytocin might ameliorate cancer pain by modulating the expression of TLR-4 and pro-inflammatory cytokines in the spinal cord." (PMID 34638587, 2021). "Interestingly, we realized that the inhibition of TLR4 boosted the cell cytotoxicity of all drugs, which indicates the fact TLR4 would confer chemo‐resistance to a broad range of anti‐cancer agents." (PMID 33336901, 2021). "This is in contrast to the results of TLR4 in CC PtAT explants and could point to shifts between different inflammasome activation routes due to tissue-specific changes during cancer cachexia progression." (PMID 34630405, 2021). "The differences observed between macrophages and cancer cells might be partially attributable to differences in the expression levels of TLR4 or other accessory molecules expressed on these cells." (PMID 34900687, 2021). "TLR4 signalling in cancer cells increases their ability to invade." (PMID 35004315, 2021). "In view of the correlation between TLR4 expression and the immune invasion level and immune checkpoints in different types of cancer, we determined the relationship between TLR4 and the prognosis of different types of cancer immune neoantigen, TMB, MSI, DNA repair genes, and DNA methylation." (PMID 34631699, 2021). "We hypothesised that HMGB1 could upregulate galectin-9 expression in cancer cells through the activation of TGF-β production induced in a TLR4-dependent manner." (PMID 34234778, 2021). "Next, we explored whether TLR4 promoted CRC growth under HFD conditions by regulating cancer metabolism." (PMID 34385421, 2021).
cancer (continued). "TLR4 mediates cancer-induced muscle wasting through p38β MAPK-mediated muscle protein loss." (PMID 34950660, 2021). "In addition, APS can activate macrophages and release NO and TNF-α by activating TLR4 and NF-κB/Rel, directly preventing the growth of cancer cells." (PMID 33935714, 2021). "TLR4 activation of cancer cells is mostly reported to promote aggressive behaviour of cancer cells, including epithelial to mesenchymal transition, migration, and invasion; furthermore, TLR4 overexpression has been correlated with increased metastasis." (PMID 34771442, 2021). "However, the relationship between TLR4 and prognosis and immune cell infiltration in pan-cancer patients is still unclear." (PMID 34631699, 2021). "While acute TLR4 activity is known to drive pro-inflammatory cytokine production, evidence is emerging that prolonged TLR4 signaling can contribute to a more immunosuppressive response, leading to immune escape by cancer cells." (PMID 33554122, 2021). "This could be of interest for staging infections, Toll-like receptor-4 (TLR-4)-induced inflammation, autoimmune processes, transplant rejection and for monitoring the effects of cancer immunotherapy." (PMID 32989622, 2021). "The expression of TLR4 gene was correlated with the target cancers." (PMID 34631699, 2021). "Also, ALR stimulates TLR-4 signaling, increased apoptosis, and decreased cancer cell attachment to the surface compared to the untreated cells." (PMID 34904014, 2021). "TLR4 was also shown to be involved in Dox-induced cardiotoxicity, and Dox was shown to induce TLR4 expression in human macrophages, mediating systemic inflammation in cancer patients." (PMID 34134693, 2021). "As TLR4 signaling is an immune-response pathway, it is likely to interplay with the role of the immune system in cancer, an aspect that we did not test in our immune-deficient model." (PMID 33554122, 2021). "Widely studied bacterial lipopolysaccharide (LPS), a major factor of the outer membrane in gram-negative bacteria, helps in activation of the host’s cell surface receptor toll-like receptor 4 (TLR4), thus in turn activating immune T cell-mediated response against a number of cancer cells." (PMID 33401586, 2021). "Biological pathway analysis revealed the downregulated DEGs are mainly enriched in vitamin A and carotenoid metabolism, wnt signaling, cancer pathway, TLR4 signaling and tolerance, G13 signaling pathway, tryptophan metabolism, differentiation pathway, IL-3, IL-4 signaling pathway." (PMID 34960172, 2021). "Therefore, the modulation of TLR4 activity is a novel target for the TLR4-mediated inflammatory response, immune disease, metabolic disease, and cancer." (PMID 33673673, 2021). "AMPKα1KO A549 cells exhibited attenuation of cancer migration and invasion induced by TLR4." (PMID 33172060, 2020). "The influence of TLR4 on cancer is two-sided, depending on where it is expressed." (PMID 33469538, 2020). "Furthermore, in some cases, the activation of certain TLRs, such as TLR2 or TLR4, can have direct antitumoral effects on cancer cells." (PMID 32984007, 2020). "Previous studies have shown that TLR4 plays a vital role in cancer development." (PMID 32095158, 2020). "Here, the authors show the TLR4-dependent adjuvant effect of FimH, an E. coli adhesin, in promoting dendritic cell mediated-T cell activation and response to immune checkpoint blockade in preclinical cancer models." (PMID 32132528, 2020). "TLR4-based intratumoral immune activation may be a viable approach to enhance the efficacy of therapeutic cancer vaccines and ACT in patients." (PMID 32579133, 2020). "TLR4 is expressed in several human cancer cell lines, such as MDA-MB-231, MCF7, A549 and H1299." (PMID 32414156, 2020). "In contrast, GBM cancer stem cells downregulate TLR4 to evade immune suppression." (PMID 32973662, 2020).